CXCL12 (C-X-C motif chemokine ligand 12)
Diseases named in the same sentence as CXCL12 in open-access papers (continued):
Sharing a sentence is not in itself a finding about the gene and the disease.
tumor (continued). "Thus, ATRA treatment of tumor bearing KPC mice resulted in an enhanced CTL infiltration in the tumor tissue, which was explained by reduced secretion of the chemokine CXCL12 by reverted stellate cells." (PMID 34638420, 2021). "Chemokine CXCL12 and its specific receptor CXC chemokine receptor 4 (CXCR4) constitute the biological axis of CXCL12/CXCR4, which are involved in inflammatory reaction, tumor formation, and other disease." (PMID 33880887, 2021). "In addition, enhanced CXCL12/CXCR4 signaling can induce cells to secrete growth factors and cytokines to create a beneficial microenvironment for tumor growth." (PMID 33962657, 2021). "A significant negative linear correlation was found between tumor growth and CXCL12 (r = −0.573, r2 = 0.329, p = 0.008, n = 20), while a positive linear correlation emerged with CXCR4 (r = 0.448, p = 0.037, r2 = 0.201, n = 23)." (PMID 34834449, 2021). "Such tumor microenvironmental factors may also affect long-distance attraction of tumor cells to the lung, the most frequent site of EwS metastasis expressing high levels of the CXCR4 ligand CXCL12." (PMID 33919988, 2021). "CAF with tumor-promoting functions secrete growth factors (HGF, IGF1, CTGF, PDGF, VEGF, LIF), cytokines (IL-1, IL-4, IL-6, IL-8, IL-10, TGF-β), and chemokines (CCL2, CCL5, CXCL5, CXCL9, CXCL10, CXCL12), WNT5α, and bone morphogenic protein 4 (BMP4), which promote tumor progression." (PMID 35008832, 2021). "Besides, there are DCs attracted by CCL-5, CCL-19, CCL-20, CCL-21, and CXCL-12 chemokines which employ regulatory Tregs and CCR-7+ DC.CCL-17 and CCL-22 working on CCR-4 are capable of straightaway recruiting Th2 and Tregs for tumour progression and spread." (PMID 34336101, 2021). "Genetic deletion of FAP in a KPC model led to decreased tumor growth, with improved immune surveillance and synergy with anti PD-1 and anti CTLA-4 therapies, an effect that resulted from a reduction in CAF-mediated CXCL12 secretion." (PMID 34948209, 2021). "Moreover, M2aM2d would favor tumor angiogenesis by secreting PDGF, TGF-β, IL-8, CXCL12, and VEGF-A, thus contributing to tumor angiogenesis metastasis." (PMID 34177892, 2021). "The most common chemokines that attract macrophages to the tumor are CCL2, CCL20, CCL5, and CXCL12." (PMID 33919517, 2021). "On the other hand, CXCR4, the receptor of CXCL12, showed heterogenous expression patterns and its expression was not correlated with the existence of senescent tumor cells in CRC tissues." (PMID 33643790, 2021). "Moreover, the expression level of CCL15 is upregulated in tumor tissues of HCC, and the expression level of CXCL12 is deregulated in HCC (R = 0.269, p = 1.45e-07; R = −0.23, p = 7.45e-06, respectively), which are consistent with PPIA expression changes." (PMID 33790943, 2021). "Tumors derived from shC‐engrafted tumor cells had the highest CXCL12 levels irrespective of the host, and shTNC‐engrafted tumor cells expressed less CXCL12 altogether pointing at the tumor cells as major source of CXCL12." (PMID 33988305, 2021). "Furthermore, we evaluated the expression of CXCL12 and its receptor CXCR4 as well as some XBP1 pathway molecules in tumor cells under different culture condition." (PMID 34093792, 2021). "Its involvement in tumor metastasis has been proven in different tumors, in which CXCR4 expression promotes the migration and metastasis of tumor cells into tissues with increased levels of CXCL12." (PMID 34575965, 2021). "A prime example is CXCL12, which together with its receptors CXCR4 and CXCR7 guide tumor cell metastatic migration, recruit stromal cells (including immune cells), promote angio- and lymphogenesis and constitute a crucial part of the CSC niche in many tumor entities." (PMID 33530455, 2021). "In the absence of supplemented CXCL12, cells seem to migrate in lower numbers, so a delayed tumor lysis was observed." (PMID 33925968, 2021).
tumor (continued). "CXCL12 affects tumor cell biology via 1) direct stimulation of signaling pathways that promote cancer cell growth, metastasis, and angiogenesis; 2) indirect effects, including the recruitment of CXCR4/CXCR7-positive cancer cells to CXCL12-expressing organs." (PMID 34540690, 2021). "The addition of stromal cells increased transcription of matrix remodelling proteins FN1 and MMP9, induced release of tumour-promoting immune molecules MIF, Serpin E1, CXCL1, IL-8 and CXCL12 and altered cancer cell expression of immunotherapeutic targets EGFR, CD47 and PD-L1." (PMID 34885111, 2021). "Tumor angiogenesis is strongly promoted by CAFs through the production of immunomodulatory and pro-angiogenic chemokines and cytokines like IL-4, IL-8, IL-6, TNF, CXCL12, TGFβ and VEGF." (PMID 33472580, 2021). "It has been found that Cabozantinib triggers the release of C-X-C motif chemokine ligand 12 (CXCL12) and high mobility group box 1 protein (HMGB1) from dying tumor cells, which mediate acute neutrophil mobilization and migration, contributing to an amplified anti-tumor response." (PMID 34830850, 2021). "We previously reported that CXCR7/AKCR3 may act as a decoy receptor for CXCL12 that counteract CXCR4-mediated LNCaP cell migration, a process that promote tumor metastasis." (PMID 33808801, 2021). "We show that inactivation of CXCL12 in ASC suppresses carcinogenic signaling, tumor growth and EMT." (PMID 33753872, 2021). "Furthermore, increased CXCL12 concentration in the TME activates the CXCL12/CXCR4 axis and enhances the recruitment of EPCs to HCC, which also promotes tumor neovascularization." (PMID 34386499, 2021). "To address whether CXCL12 is the major chemoattractant by which TNC immobilizes CD8 T cells, we used conditioned medium (CM) from cultured tumor cells in the migration and retention assay, respectively." (PMID 33988305, 2021). "Tumor growth correlated inversely with CXCL12 and positively with CXCR4 expression, suggesting that local CXCL12 may impair the primary tumor cell response to the ligand gradient that may contribute to driving the tumor progression." (PMID 34834449, 2021). "We discriminated 4 staining intensities with no or low CXCL12 and high CXCL12 in tumor nests only, or combined high expression in tumor nest and stroma." (PMID 33988305, 2021). "For instance, by secreting cytokines such as CXCL12, activated PSCs are able to facilitate the trafficking of CD8 + T cells away from the juxta-tumoral compartment and thus reduce the frequency of infiltrating CTLs in tumor islets." (PMID 34635121, 2021). "Both the lung and the bone marrow express high CXCL12 levels, and CXCL12 gradients may be responsible for long-distance attraction and binding to CXCR4-positive tumor cells." (PMID 33919988, 2021). "Moreover, it was reported that high levels of CXCL12 (SDF-1) are secreted by MSCs that regulate the migration and invasion of CXCR4-expressing tumor cells." (PMID 33472580, 2021). "Chemokines and their receptors, principally the chemokine (C-X-C motif) ligand 12 (CXCL12) and its receptor CXCR4, have gained attention for their functional roles as being able to communicate between tumor cells and the tumor microenvironment including immune and vascular cells as also the stroma." (PMID 34445691, 2021). "In many types of cancers, tumor cells secrete the chemokine CXCL12 to induce the infiltration of a large number of immature pDCs, and the cytokines of VEGF, TNF-α, TGF-β and IL-10 secreted in tumor microenvironment inhibit the maturation and activation of pDCs, then make it unable to produce IFN-α." (PMID 34737750, 2021). "The accumulation of MSCs within the tumor stroma is also supported by increasing cytokine concentrations of fibroblast growth factor-2, monocyte chemotactic protein-1 (=CCL2), CCL5, and stromal cell-derived factor 1 (=CXCL12)." (PMID 34680359, 2021).
tumor (continued). "Hypoxic tumor cells around dying tumor cells in the TC can also produce various kinds of cytokines regulated by HIF, such as C–C chemokine ligand type 5 (CCL5), CXCL12, vascular endothelial growth factor A (VEGF-A), endothelin (ET)-1, ET-2 and semaphorin-3A (Sema3A)." (PMID 34172088, 2021). "Factors that can promote the anti-tumor neutrophil phenotype include chemokines (e.g., CXCL2, CXCL5, CXCL8, CCL2, CCL3, CCL5, CXCL12 (SDF-1), CXCL16 and IL-8) alone or together with G-CSF/GM-CSF, TNFα, IFNβ, IFNγ, IFNγ together with TNFα, Resolvin D1, hepatocyte growth factor (HGF) and IL-17." (PMID 34572138, 2021). "Another study on axillary lymph nodes further indicated that the CAF-S1 subset promotes cancer cell migration and EMT initiation mainly by secreting CXCL12 and TGF-β, while the CAF-S4 subset facilitates the migration and invasion of tumor cells through the NOTCH pathway." (PMID 34635121, 2021). "We investigated by flow cytometry whether TNC influenced CD8 TIL function in vivo through CXCL12, by blocking CXCR4 with AMD (for 2 weeks) in tumor‐bearing mice in the 4‐week model (Figs EV2 and EV4A–H)." (PMID 33988305, 2021). "Increased secretion of IL-6, TNFα, CCL2, CCL5, CXCL9 and GM-CSF, which are pro-inflammatory factors combined with decreased secretion of anti-inflammatory factors including IL-4, IL-28A, CCL24, CXCL12 and SCF from infected HEL299 fibroblasts, is expected to be tumor-promoting and enhance metastasis." (PMID 34575976, 2021). "Indeed, Ac-KLF5 transactivates the CXCL12/CXCR4 chemokine axis, IL-11 cytokine signaling, and likely other paracrine molecules in tumor cells, as revealed by RNA-Seq, ChIP-Seq, and related analyses." (PMID 33731701, 2021). "Recent studies indicated that prolonged stimulation of MSCs by tumor-derived factors could lead to their conversion to CAFs, as did TME-derived factors such as transforming growth factor β, CXCL12, and osteopontin." (PMID 33806906, 2021). "This may be partly due to other tumor-derived factors also attract circulating monocytes to the tumor site and differentiate into TAMs, such as CSF1, CCL5, CXCL12 and CX3CL1." (PMID 33564072, 2021). "CXCR4 is widely expressed in many tissues and CXCL12/CXCR4 signaling plays an important role in diverse processes such as cell proliferation, survival, and differentiation, as well as inflammatory responses and tumor development." (PMID 33962657, 2021). "Likewise, blocking CXCL12/CXCR4 using AMD3100 significantly inhibited tumor growth and metastasis, and the combination of AMD3100 and anti-PD-1 further reduced tumor growth and metastasis." (PMID 34911533, 2021). "CXCL12 has a pervasive influence in PDAC by increasing proliferation, enhancing invasion and metastasis, and promoting chemoresistance and immune evasion of tumor cells." (PMID 35008248, 2021). "CXCL12 secreted by TECs, compared to normal endothelial cells (NECs), promotes CXCR7-mediated angiogenesis via ERK1/2 suggesting an autocrine/paracrine loop between tumor and TECs." (PMID 33937018, 2021). "The mRNA level of CXCL12, F3, PHLDA1, and ZEB2 was upregulated in the tumor samples." (PMID 33808801, 2021). "The administration of the nanoparticles suppressed CXCL12 secretion and ECM deposition upon photoirradiation, leading to significantly reduced the immunosuppression, enhanced T cell infiltration, followed by efficient tumor suppression." (PMID 34305902, 2021). "Thus, we argue that the CXCL12/CXCR4 axis activates immunosurveillance via a mechanism (which we name Immunogenic Surrender) that allows tumor identification by innate cells and tumor‐specific T‐cell priming." (PMID 33956406, 2021). "Additionally, NO nitrifies chemokine such as CXCL12, CCL21, CCL2, or CCL5, reducing chemokine-induced T cells migration and tumor infiltration." (PMID 34680276, 2021).
tumor (continued). "In the GEPIA database, the results indicated that the expressional levels of CXCL1/8/9/10/11/13/16/17 were increased in tumor tissues rather than normal tissues, while CXCL12 was reduced." (PMID 34321012, 2021). "Data from our study and previous reports suggest that increased tumor infiltration of neutrophils induced by cabozantinib might be due to the increased neutrophil-related chemokines CCL11 and CXCL12 in the tumor microenvironment." (PMID 33954115, 2021). "In addition, CAFs can promote irradiated cancer cell recovery and tumor relapse after RT by producing insulin-like growth factor-1/2 (IGF-1/2), C-X-C motif chemokine ligand 12 (CXCL12), and β-hydroxybutyrate." (PMID 34646829, 2021). "Hypoxia inducible factor (HIF)-1 stimulates the local production of factors, including stromal cell-derived factor 1 (SDF1, also known as C-X-C motif chemokine 12, (CXCL12) which promotes the recruitment of bone marrow EPC and CD45+ myeloid cells to the tumor site." (PMID 33921099, 2021). "This revealed that the intertwining between CXCL12, mainly expressed by nerve tissue in the SACC specimens with PNI and CXCR4, strongly expressed by tumour cells at nerve invasion frontier might offer favourable terms for the initiation of PNI in SACC." (PMID 34170080, 2021). "Interestingly, IL-6, CXCL12, RANKL, CCL2, and TGFβ secreted by both tumor and bone stromal cells are well-studied cytokines that have been implicated in induction of this process." (PMID 32585812, 2020). "The CXCR4 ligand CXCL12 and the CX3CR1 ligand CX3CL1 were downregulated in the tumour tissue." (PMID 32439888, 2020). "Further, it has been shown that CAF-derived CXCL12 may function as an important EMT inducer BC cells by regulating the Wnt/β-catenin signaling pathway, thus promoting tumor cell migration and invasion." (PMID 32466591, 2020). "Similarly, in BC, a subset of myofibroblastic CAFs (CAF-S1: CD-29Med FAPHi FSP-1Low−Hi αSMAHi PDGFRbMed−Hi CAV-1Low) secreting differentially higher amount of CCL-11, CXCL-12, CXCL-13, and CXCL-14 was predominantly detected close to epithelial tumor cells." (PMID 33553157, 2020). "Tregs are known to accumulate in tumor tissues and this is mainly promoted by CC chemokine receptor 4 (CCR4)-CC motif ligand 17/22 (CCL17/22), CCR10-CCL28, and CXC chemokine receptor 4 (CXCR4)-CXC motif ligand 12 (CXCL12)." (PMID 32626535, 2020). "Moreover, CXCL12, CXCL8, or RANKL released into TME have been found capable of upregulating MMP production and breaking down ECM to induce increased tumor cell invasiveness." (PMID 32585812, 2020). "CXCL12 is a chemokine ubiquitously expressed in many tissues and cell types, and the interaction of CXCL12 and its receptor, CXCR4, is involved in multiple processes in the tumor microenvironment." (PMID 33261029, 2020). "Inhibition of the CXCR4-CXCL12 axis, on the other hand, can sensitize cancer cells to chemotherapy or radiotherapy by inhibiting the interaction between the CXCR4-expressing tumor cells and stromal cells, resulting in decreased cancer cell protection by the CXCL12 releasing stromal cells." (PMID 31802362, 2020). "The relative expression of COL1A1, IGF1, COL5A1, CXCL12, and PTEN in tumor samples was significantly lower compared to those in adjacent normal samples (P < 0.05), while SPP1 expression was significantly higher in tumor samples compared to the adjacent normal samples (P < 0.05)." (PMID 32641130, 2020). "Regardless of the tumor type or tumor site, Ly6c1high CAFs (iCAFs) showed enrichment for Il33, Il6, Ccl7, Cxcl1 and Cxcl12 whereas α-SMAhigh CAFs (myCAFs) expressed high levels of Tgfb1, Tgfb2 and Ctgf." (PMID 32455670, 2020). "Moreover, the CXCL12/CXCR4 cascade affects both immune and stromal cells, creating tumor-supporting microenvironment." (PMID 33096815, 2020).
tumor (continued). "In human iCCA tissues TNF-α is mainly expressed in infiltrating macrophages, while CXCR4 is present in cancer cells but not in non-neoplastic ducts and CXCL12 in stromal fibroblasts and, to a lesser extent, in tumor cells." (PMID 32784743, 2020). "However, further investigation indicated that SELNs induce the activation of NFκB, the expression and secretion of CXCL12, and stimulation of CXCR4/AKT survival pathway, resulting in protection of these tumor cells from death." (PMID 33363463, 2020). "Nonetheless, studies to date indicate that the CXCL12 axis is a tumor promoter rather than a tumor initiator." (PMID 33363463, 2020). "Furthermore, CAFs can promote irradiated cancer cell recovery and tumor relapse after RT by producing insulin-like growth factor-1/2 (IGF-1/2), C-X-C motif chemokine ligand 12 (CXCL12), and β-hydroxybutyrate." (PMID 33050580, 2020). "iDCs are attracted to tumor tissue sites through CCL20, CXCL12, and CXCL14 chemotaxis." (PMID 31991604, 2020). "In addition, CXCL12/CXCR4 is involved in vessel co-option and trafficking of leukocytes to the tumor." (PMID 31690961, 2020). "Blocking CXCL12/CXCR4 signaling between pancreatic cancer cells and CAFs could attenuate RT-induced tumor cell invasion." (PMID 33050580, 2020). "The CXCL12/CXCR4 interaction phosphorylates CXCR4, subsequently promotes calcium flux, and directly activates MAPK, PI3K, Wnt, and Sonic Hedgehog signaling pathways, thus inducing proliferation of various types of tumor cells." (PMID 33363463, 2020). "Moreover, cancer cells have been found to home in on tissues with high levels of CXCL12 expression and to increase their own secretion of CXCL12 to attract CXCR4-expressing stromal cells that can, in turn, assist with tumor development." (PMID 33521055, 2020). "Interestingly, these pathways are utilized by a series of chemokines and their receptors, such as CCL20/CCR6, CCL25/CCR9, CXCL1/CXCR2, CXCL8/CXCR1-2, CXCL12/CXCR4, and CX3CL1/CX3CR1, to inhibit apoptosis and promote tumor cell growth and proliferation." (PMID 31991604, 2020). "It indicated that the COL1A1, IGF1, COL5A1, CXCL12, PTEN, and SPP1 were significantly differently expressed in EC tumor compared with those in normal samples (P = 4.93E−02, P = 5.24E−03, P = 2.83E−04, P = 1.58E−06, P = 2.11E−12, and P = 6.91E−13, respectively)." (PMID 32641130, 2020). "TAMs participate in the tumour angiogenesis by secreting pro‐angiogenic factors, including VEGF‐A, EGF, PlGF, TGF‐β, TNF‐α, IL‐1β, IL‐8, CCL2, CXCL8 and CXCL12, and enable tumour metastasis by up‐regulated N‐cadherin and Snail, whereas down‐regulated E‐cadherin." (PMID 32588948, 2020). "Moreover, we also found that elevated circ_0020710 was correlated with cytotoxic lymphocyte exhaustion, and a combination of AMD3100 (the CXCL12/CXCR4 axis inhibitor) and anti-PD-1 significantly attenuated tumor growth." (PMID 32381016, 2020). "Because CXCR4 is induced in EWS cells exposed to hypoxia, a common condition of human tumor microenvironment, we investigated the contribution of the IGF2BP3/CD164/CXCR4 axis on CXCL12-evoked biological responses of EWS cells under normoxic (21% O2) or hypoxic conditions (1% O2)." (PMID 32719743, 2020). "Thus, CXCL-12 signaling by receptor CXCR-4 requires an intimate interaction between CAFs and tumor cells, which would result in the proliferation of tumor cells as well as acceleration of neo-angiogenesis due to the recruitment of endothelial progenitor cells." (PMID 33585565, 2020). "Calcipotriol was shown to induce lipid droplet formation in PDAC PSCs, reduce tumor volume and stromal density, improve tumor vascularity, increase intra-tumoral gemcitabine (by 500%), block TGF-β/SMAD signaling and decrease the release of IL-6, CTGF and CXCL12." (PMID 32532126, 2020). "Importantly, FAP+ CAFs are also the main producers of CXCL-12 in PDAC, and their specific depletion increases immunological control over tumor growth." (PMID 33553157, 2020).